F7 (coagulation factor VII)
Description:
Initiates the extrinsic pathway of blood coagulation. Serine protease that circulates in the blood in a zymogen form. Factor VII is converted to factor VIIa by factor Xa, factor XIIa, factor IXa, or thrombin by minor proteolysis. In the presence of tissue factor and calcium ions, factor VIIa then converts factor X to factor Xa by limited proteolysis. Factor VIIa also converts factor IX to factor IXa in the presence of tissue factor and calcium.
Synonyms: SPCA
Tractability: Small molecule: a drug acting on it is in phase 2 or 3 trials; a structure with a bound ligand is known; a high-quality ligand is known; it has a binding pocket of medium quality; it belongs to a druggable protein family. Antibody: UniProt places it where antibodies can reach, with high confidence; its Gene Ontology location is reachable by antibodies, with high confidence; UniProt predicts a signal peptide or a membrane-spanning region. PROTAC: a small molecule that binds it is known. Other modalities: an approved drug acts on it.
Target class: Serine protease; Enzyme; Serine protease PA clan; Serine protease S1A subfamily; Protease
Chemical probes: BCX-3607
Gene: Protein-coding gene on chromosome 13 (113,105,762 to 113,120,685, forward strand). Ensembl gene ENSG00000057593.
Subcellular location: Secreted
Pathways (Reactome):
Metabolism of proteins: Gamma-carboxylation of protein precursors; Removal of aminoterminal propeptides from gamma-carboxylated proteins; Transport of gamma-carboxylated protein precursors from the endoplasmic reticulum to the Golgi apparatus
Hemostasis: Initiation of coagulation cascade; Regulation of clotting cascade
Circadian clock: BMAL1:CLOCK,NPAS2 activates circadian expression
Gene Ontology:
Molecular function: protein binding; serine-type endopeptidase activity; serine-type peptidase activity; calcium ion binding; endopeptidase activity; signaling receptor binding
Biological process: blood coagulation; positive regulation of leukocyte chemotaxis; positive regulation of platelet-derived growth factor receptor signaling pathway; positive regulation of positive chemotaxis; positive regulation of TOR signaling; protein processing; positive regulation of cell migration; animal organ regeneration; circadian rhythm; positive regulation of blood coagulation; proteolysis; regulation of body fluid levels; response to 2,3,7,8-tetrachlorodibenzodioxine; response to astaxanthin; response to carbon dioxide; response to cholesterol; response to estradiol; response to estrogen; response to genistein; response to growth hormone; response to hormone; response to hypoxia; response to nutrient levels; response to stress; response to thyroid hormone; and 4 more
Cellular component: extracellular matrix; extracellular region; serine-type peptidase complex; endoplasmic reticulum lumen; Golgi lumen; plasma membrane; vesicle
Genetic constraint (gnomAD): Loss-of-function variants: 38 observed, 44.77 expected, observed/expected ratio (o/e) 0.85, 90% interval 0.65 to 1.11. The upper end of that interval is the gene's LOEUF score, 1.11, which puts it in group 4 of 6, group 1 being the genes least tolerant of losing a copy. Missense variants: 575 observed, 599.76 expected, observed/expected ratio (o/e) 0.96, 90% interval 0.89 to 1.03. Synonymous variants: 244 observed, 256.58 expected, observed/expected ratio (o/e) 0.95, 90% interval 0.86 to 1.06.
Gene-disease validity (ClinGen):
ClinGen rates the evidence that F7 causes each of these diseases.
factor VII deficiency (autosomal recessive): Definitive.
Homologues: Orthologues: chimpanzee F7 (99% identical), macaque F7 (93% identical), dog F7 (76% identical), pig F7 (73% identical), mouse F7 (70% identical), rat F7 (69% identical), guinea pig F7 (68% identical), tropical clawed frog f7 (53% identical), zebrafish f7 (45% identical), zebrafish f7l (43% identical), zebrafish f7i (41% identical). Paralogues in human: F9 (42% identical), F10 (41% identical), HGFAC (27% identical), KLKB1 (27% identical), C1S (27% identical), F11 (26% identical), F12 (25% identical), C1R (25% identical), CFI (24% identical), PRSS55 (19% identical), C1RL (19% identical), HP (18% identical), and 4 more.
Diseases named in the same sentence as F7 in open-access papers:
F7 is named in the same sentence as 196 diseases in open-access papers, as found by Europe PMC text mining. Sharing a sentence is not in itself a finding about the gene and the disease. The quoted sentences say what the papers report.
hemophilia A (21 papers, 2009 to 2026). The most common form of hemophilia characterized by spontaneous or prolonged hemorrhages due to factor VIII deficiency. "Therefore, the rate of congenital coagulation disorders (congenital coagulation factor VII and hemophilia A) was 13% in the current cohort." (PMID 33569364, 2021).
hemophilia (20 papers, 2012 to 2025). Hemophilia is a genetic disorder characterized by spontaneous hemorrhage or prolonged bleeding due to factor VIII or IX deficiency. "Actually, exogenous recombinant activated coagulation factor VII (F7), as an adjunctive therapy, can successfully help to urgently stop internal bleeding caused by acquired hemophilia as an autoimmune complication of RA, which is treated with immunosuppressive therapy at the same time." (PMID 34239535, 2021). "One of the valuable members, involved in extrinsic pathway, is coagulation factor VII and related biopharmaceuticals have been administered as a replacement therapy in hemophilia and non-hemophilia bleeding disorders 11–13." (PMID 28496951, 2017).
coagulopathy (19 papers, 2006 to 2025). "We have also sequenced the coagulation factor VII gene of 141 animals to assess the presence of a previously reported hereditary coagulation disorder in Asian elephants and to investigate the presence of other mutations." (PMID 35158684, 2022). "Coagulopathy in a cirrhotic patient is related to a reduction of coagulation factors, and the presence of anti-coagulants, thrombocytopenia, deficit of factor VII, and increased plasma levels of coagulation factor VIII and Von Willebrand factor." (PMID 33620540, 2021). "We suggest that the use of recombinant activated coagulation factor VII (rFVIIa) be considered if major bleeding and traumatic coagulopathy persist despite standard attempts to control bleeding and best-practice use of conventional haemostatic measures." (PMID 23601765, 2013).
bleeding disorders (16 papers, 2010 to 2026). "One of these had F7 deficiency together with another bleeding disorder (von Willebrand syndrome)." (PMID 37521340, 2023). "Coagulation factor VII is a plasma serine protease that has a significant role in natural human hemostasis and its recombinant form such as AryoSevenTM, has been applied in clinical treatment of bleeding disorders." (PMID 28496951, 2017). "Factor VII deficiency is the most common among rare inherited autosomal recessive bleeding disorders, and is a chameleon disease due to the lack of a direct correlation between plasma levels of coagulation Factor VII and bleeding manifestations." (PMID 28350321, 2017).
hypercoagulability (15 papers, 2010 to 2025). "This is consistent with the results reported by Ordookhani and Burman, who considered the increased coagulation factor VII and plasminogen activator inhibitor-1 activity to be one of the main mechanisms leading to the hypercoagulable state in patients with hypothyroidism." (PMID 32461982, 2020).
thrombosis (11 papers, 2009 to 2025). "Proteins related to venous thrombosis and blood coagulation, such as Coagulation factor VII (F7) and Fibrinogen alpha chain (FGA), were upregulated in the ZIKV group." (PMID 33312964, 2020).
coronary heart disease (9 papers, 2007 to 2023). "Previous studies have examined the association between polymorphisms in the coagulation factor VII gene and the risk of coronary heart disease (CHD), but those studies have been inconclusive." (PMID 21838885, 2011).
breast carcinoma (8 papers, 2010 to 2021). "The coagulation factor VII (F7) participates in maintaining vascular hemostasis and promotes breast cancer cell proliferation, invasion and metastasis." (PMID 29202775, 2017).
Obesity (6 papers, 2015 to 2024). Accumulation of substantial excess body fat. "Higher levels of the protein F7 (coagulation factor VII) have been linked to cardiovascular disease and obesity, while previous research indicates that proteins ACY1 (aminocyclase 1) and GSTA1 (glutathione S-transferase alpha 1) are positively associated with T2D." (PMID 38337712, 2024).
Sepsis (5 papers, 2015 to 2021). Sepsis is defined as life-threatening organ dysfunction caused by a dysregulated host response to infection. "This would be similar to plasma EVs in sepsis and cancer patients that have been shown to contain coagulation factor VII and tissue factor." (PMID 29286309, 2017).
endothelial dysfunction (3 papers, 2023 to 2026). In vascular diseases, endothelial dysfunction is a systemic pathological state of the endothelium (the inner lining of blood vessels) and can be broadly defined as an imbalance between vasodilating and vasoconstricting substances produced by (or acting on) the endothelium. "Vaccination against Salmonella Typhii (ST) induces a mild systemic inflammation with similar cardiovascular effects, such as endothelial dysfunction, increased vascular stiffness and activation of coagulation factor VII, as a myocardial infarction." (PMID 41403875, 2026). "However, the model is well-documented with a small rise in IL-6 with a magnitude similar to the rise associated with non-ST-elevation myocardial infarction with cardiovascular consequences, such as endothelial dysfunction, increased vascular stiffness and activation of coagulation factor VII." (PMID 41403875, 2026).
ovarian carcinoma (3 papers, 2009 to 2021). A malignant neoplasm originating from the surface ovarian epithelium. "The hypoxia-inducible factor 2α (HIF2α)–SP1 complex activated coagulation factor VII promoter in OCCC and estrogen receptor α also form complexes with SP1 in other types of ovarian cancer 31,32." (PMID 25060396, 2014).
Thromboembolism (3 papers, 2015 to 2025). The formation of a blood clot inside a blood vessel that subsequently travels through the blood stream from the site where it formed to another location in the body, generally leading to vascular occlusion at the distant site. "The link between the ABO blood type and thromboembolic diseases and bleeding risk is intervened by the glycosyltransferase activity and plasma levels, and the biologic activity of Von Willebrand factor, a carrier protein for coagulation factor VII which is low in the blood group 0." (PMID 37568521, 2023).
Hypertension (2 papers, 2023 to 2024). The presence of chronic increased pressure in the systemic arterial system. "Plasma levels of kallikrein, thrombin, and coagulation factor VII are elevated in prediabetes, which can lead to hypertension and cardiovascular disease." (PMID 37753042, 2023).
metabolic syndrome (2 papers, 2011 to 2023). A cluster of metabolic risk factors for CARDIOVASCULAR DISEASES and TYPE 2 DIABETES MELLITUS. "Other studies have shown a correlation between elevated levels of coagulation factor VII and various risk factors for cardiovascular disease, dyslipidemia, and insulin resistance." (PMID 38092892, 2023). "Finally, Coagulation factor VII is a protein that is involved in the blood coagulation cascade, and its dysregulation may contribute to an increased risk of cardiovascular disease, which is associated with metabolic syndrome." (PMID 38092892, 2023).
prostate carcinoma (2 papers, 2016 to 2021). A carcinoma that arises from epithelial cells of the prostate gland. "Angiogenesis of prostate cancer was inhibited possibly via suppressor of cytokine signaling 6 (SOCS6) overexpression-mediated F7 downregulation." (PMID 34066023, 2021). "Because prostate cancer cells do not express Factor VII, there is no mRNA target for the murine TBG-RNAi-F7 oligomer, and therefore no induction of GW bodies would be anticipated in the control tumors." (PMID 27557516, 2016).
venous thromboembolism (2 papers, 2019 to 2024). Occlusion of the lumen of a vein by a thrombus that has migrated from a distal site via the blood stream. "Prothrombin, coagulation factor X, coagulation factor VII and tissue factor exhibited vital modulation function in hypercoagulability state and venous thromboembolism of COPD17,37." (PMID 31530860, 2019).
Atrophy (1 paper, 2024). Any weakening or degeneration, especially through lack of use. "Genetic variants associated with decreased levels of pathogenic proteins ITGB6 (rs8099840), TLR5 (rs1403631, rs75118229), F7 (rs6046), HERC5 (rs406936) and MGA (rs704) were associated with preserved brain volumes over time, including in regions susceptible to infection-specific atrophy." (PMID 39143319, 2024).
depression (1 paper, 2021). "The results show that Fibrinogen alpha chain (FGA), Fibrinogen beta chain (FGB), Fibrinogen gamma chain (FGG) and Coagulation factor VII (FVII) were screened in the EC pathway from depression patient samples." (PMID 34488523, 2021).
hereditary spastic paraplegia (1 paper, 2016). Hereditary spastic paraplegias (HSP) comprise a genetically and clinically heterogeneous group of neurodegenerative disorders characterized by progressive spasticity and hyperreflexia of the lower limbs. "Given that the symptoms were not justified by the deficiency of coagulation factor VII and on suspicion of hereditary spastic paraplegia (HSP), tests were carried out." (PMID 28018685, 2016).
Hypoglycemia (1 paper, 2025). A decreased concentration of glucose in the blood. "Nevertheless, in experimental models, elevated catecholamines due to hypoglycemia have been associated with blood coagulation abnormalities, including the activation of platelets and coagulation factor VII." (PMID 40150028, 2025).
left ventricular hypertrophy (1 paper, 2014). Enlargement of the LEFT VENTRICLE of the heart. "In multiple-phenotype analyses we find association of NRG1 with left ventricular hypertrophy phenotypes, fibrinogen and urea and pleiotropic relationships of F7 and F10 with Factor VII, Factor IX and cholesterol levels." (PMID 25329069, 2014).
pancreatic cancer (1 paper, 2011). "For example, fibrinogen gamma were found to be over-expressed in pancreatic cancer, some coagulation factors were reported to be candidate cancer biomarkers, and coagulation factor VII even can be secreted by cancer cell themselves." (PMID 22087286, 2011).
cancer (27 papers, 2010 to 2024). A tumor composed of atypical neoplastic, often pleomorphic cells that invade other tissues. "When TF-positive extracellular vesicles shed from cancer cells are associated with coagulation factor VII (FVII), this can trigger the blood coagulation cascade, leading to cancer-associated VTE." (PMID 37940761, 2024). "F3 (tissue factor III) encodes a glycoprotein receptor for coagulation factor VII and initiates blood coagulation, but has also been implicated in cancer metastasis." (PMID 31217031, 2019). "It promotes the hypercoagulable state in cancer patients by acting as a high-affinity receptor for coagulation factor VII." (PMID 35480305, 2022). "The binding of F7 to tissue factor (F3) initiates the blood coagulation cascade and F3 plays a critical role in cancer development." (PMID 27409342, 2016). "Furthermore, mesenchymal-like cancer-derived EVs that exhibited an upregulated tissue factor, a transmembrane receptor for the coagulation factor VII/VIIa, affected the procoagulant activity of endothelial cells and led to cancer malignancy." (PMID 31078138, 2019). "In addition to fibrin, additional studies have considered the role of thrombin, PAR-1, and coagulation factor VII (FVII), and their association with enhancement in cancer cell viability, cancer growth and dissemination, increased tumor malignancy, and metastatic support." (PMID 28762014, 2017). "Despite the cancer cells captured by F7 or SP peptide were identified as CSCs that expressed CD44, single peptide binding cells (F7+ or SP+) and double peptides binding cells (F7+ /SP+) were considered as different subpopulations that exist at the different stages of cancer." (PMID 34789743, 2021).
tumor (26 papers, 1992 to 2025). "F3, encoding coagulation factor III, a high-affinity receptor that induce the activation of coagulation factor VII, thereby increasing VTE risk in various tumor types." (PMID 39179711, 2024). "Induction of apoptosis (p < 0.05) coincided with suppression of Bcl2 and Hspa1a, and suppression of tumor angiogenesis coincided with suppression of F7, Fak3 and Frzb (involved in the regulation of growth and differentiation of certain cell types)." (PMID 35330327, 2022). "HABP2 is involved in coagulation and fibrinolysis systems by activating coagulation factor VII and may function as a tumor suppressor, negatively regulating cell proliferation and cell migration." (PMID 38892353, 2024). "However, more detailed information regarding the binding of F7 and SP peptides to nucleolin and vimentin respectively is required for the potential application of these tumor targeting peptides in detection and isolation approaches." (PMID 34789743, 2021). "Coagulation factor VII (FVII) can specifically bind to TF with high affinity, so the FVII-TF interaction provides an ideal target for tumor therapy." (PMID 34109110, 2021). "Tumor cells could express tissue factor which consequently interacts with coagulation factor VII (FVII) and coagulation factor X (FX) to generates thrombin to enhance tumor progression." (PMID 23861980, 2013).
infection (4 papers, 2012 to 2024). The state of being infected such as from the introduction of a foreign agent such as serum, vaccine, antigenic substance or organism. "The upregulation of F7 and F10 (Coagulation Factor VII and X) at 1d postpartum [FC = 6.44 and 5.01] also is noteworthy, because it is known that the coagulation system plays an important role in the innate immune system, particularly in the early host response to infection." (PMID 29724161, 2018).
F7 also shares sentences with these, for which no sentence is quoted: cardiovascular disease (10 papers); Glanzmann thrombasthenia (9); diabetes (7); Hyperglycemia (7); COVID-19 (6); ischemic stroke (6); liver disease (6); Stroke (6); atherosclerosis (5); hematoma (5); myocardial infarction (5); Thrombocytopenia (5); Von Willebrand disease (5); factor deficiencies (4); hemophilia B (4); intracranial hemorrhage (4); lupus (4); type 2 diabetes (4); cardiac arrest (3); congenital factor VII deficiency (3); Disseminated intravascular coagulation (3); hemarthrosis (3); hepatoma (3); hypothyroidism (3); Insulin resistance (3); metabolic disorders (3); pneumonia (3); Acute Myelogenous Leukemia (2); afibrinogenemia (2); blood disorders (2).
A further 140 diseases each share a sentence with F7 in 2 papers or fewer.